ORAI1 (ORAI calcium release-activated calcium modulator 1)
Diseases named in the same sentence as ORAI1 in open-access papers (continued):
Sharing a sentence is not in itself a finding about the gene and the disease.
prostate carcinoma (continued). "A previous study using DU145 cells reported that prostate cancer cell migration was regulated by the blockage of ORAI1 by 2-APB, enhancing the therapeutic efficacy of the Na+/K+ ATPase inhibitor." (PMID 36139707, 2022). "Several previous studies explored the possible role of SOCE/STIM1/Orai1 in autophagy using certain cell types including hepatoma cells, prostate cancer cells, and endothelial progenitor cells; however, the conclusions were inconsistent." (PMID 34079454, 2021). "In prostate cancer, Orai3 upregulation is associated with SOCE attenuation and formation of Orai1/Orai3 heteromers regulated by AA." (PMID 34768857, 2021). "Downregulation of Orai1 decreased prostate cancer cell growth, suggesting that both isoforms Orai1 and Orai3 are indispensable to drive prostate cancer cell development." (PMID 34360783, 2021). "The dynamic regulation of Orai1 to boost endogenous SK3 channels was also determined in the human prostate cancer cell line LNCaP." (PMID 34944977, 2021). "In prostate cancer, less is known about the potential relevance of the Orai1 and K+ channel interplay." (PMID 34944977, 2021). "Nevertheless, in both studies, the formation of Orai1-Orai3 heterooligomeric ARC channels has been found to play a role in prostate cancer cell development." (PMID 34360783, 2021). "On the other hand, in prostate cancer, Orai1-mediated SOCE sensitized cells to apoptosis in anti-androgen-resistant cells." (PMID 32575848, 2020). "We have previously shown that in the prostate cancer cell line LNCaP a low number of Orai3 subunits within store-operated CRAC channels alters the 2-APB response compared to Orai1-mediated currents when 50 μM was applied." (PMID 32252254, 2020). "CRACR2A in co-regulation with STIM1 and Orai1 has been recently suggested to potentially act as an upstream regulator of prostate cancer progression." (PMID 33333945, 2020). "Another interesting finding places Orai1–Orai3 channel complexes in the center of attention in a variety of prostate cancer cells." (PMID 30935064, 2019). "These suggest that endogenous SOCE mediated by Orai1 has a pivotal role in triggering apoptosis of prostate cancer cells." (PMID 31252656, 2019). "The potential importance of the ORAI3/ORAI1 heteromeric channel should now be explored in basal breast cancers and TNBCs, as has been assessed in prostate cancer." (PMID 30754719, 2019). "In prostate cancer cells, low Orai1 expression was shown to contribute to the establishment of an apoptosis-resistant phenotype, irrespective of the apoptosis-inducing stimulus." (PMID 30884858, 2019). "Extending these results, the store-independent entry was recently associated with prostate cancer-specific enhanced expression of ORAI3 and formation of a heteromeric channel with ORAI1." (PMID 29671777, 2018). "The recent characterization of store-operated calcium entry (SOCE) channel components STIM1 and ORAI1 in prostate cancer sheds light on the involvement of calcium in these processes." (PMID 29671777, 2018). "It was found that the expression of both STIM1 and ORAI1 correlated negatively with the Gleason score (the commonly used histopathological assessment of prostate cancer progression) and was lower in prostate carcinomas relative to the normal tissue." (PMID 29671777, 2018). "Among them, TRPV6 is overexpressed in a number of cancer cell types and participates in the progression of prostate cancer, acquiring its oncogenic potential via Orai1/TRPC1-dependent translocation to the plasma membrane." (PMID 30223530, 2018). "A study by our group found a slightly decreased Orai3/Orai1 ratio in prostate cancer tissue compared to normal prostate tissue." (PMID 29951353, 2017). "We here summarize findings on gene expression levels and functions of SOCE components, stromal interaction molecules (STIM1 and STIM2), and members of the Orai protein family (Orai1, 2, and 3) in prostate cancer." (PMID 29951353, 2017).
prostate carcinoma (continued). "Taken together, these findings show that the Orai1/Orai3 ratio is higher in prostate cancer cells than in healthy tissue, which is consistent with the observation that Orai1 is elevated in early clinically localized cancer stage." (PMID 29951353, 2017). "STIM1 and Orai1 expression levels are differentially regulated depending on the prostate cancer stage." (PMID 29951353, 2017). "For Orai1, 5 out of 7 studies reported a slight elevation in ORAI1 gene expression in prostate cancer tissue, only 2 out of 12 studies reported an elevation in ORAI2 gene expression." (PMID 29951353, 2017). "Recent reports on Orai1 and Orai3 expression levels and function were in part controversial probably due to the heterogeneous nature of prostate cancer." (PMID 29951353, 2017). "In early clinically localized cancer stages, STIM1 and Orai1 expression is increased, while in the later castration-resistant prostate cancer stages, their expression levels are decreased." (PMID 29951353, 2017). "The clinical diagnostic and prognostic potential of Orai1 and STIM1 have also been demonstrated in many cancer types, including prostate cancer, melanoma, NSCLC, and colorectal cancer." (PMID 27677589, 2016). "In this study, we explored the role of STIM1 and ORAI1 in tumor senescence, migration and microenvironment and demonstrated their dual functions during prostate cancer progression." (PMID 26257076, 2015). "Firstly, down-regulation of SOCE activation and reduction of Orai1 expression were observed by this laboratory and others in prostate cancer cells representing advanced stage." (PMID 24797725, 2014). "Our latest work showed Orai1 protein represents the major molecular component of endogenous store-operated Ca2+ entry in human prostate cancer cells, and constitutes the principal source of Ca2+ influx used by the cell to trigger apoptosis." (PMID 23049826, 2012). "Notably, in steroid-deprived prostate cancer cells, ORAI1 downregulation confers resistance to cisplatin-induced apoptosis." (PMID 38672434, 2024). "Moreover, Ohmline has been reported to interfere with the co-regulation of SK3 and Orai1 that is crucial in breast, colon, and prostate cancer progression (see Section 5)." (PMID 36612099, 2022). "It is tempting to speculate that Enzalutamide treatment enforces the co-regulation of SK3/Orai1 in LNCaP cells and allows a more intensive study of key determinants mediating the SK3–Orai1 interplay in this prostate cancer cell line." (PMID 36612099, 2022). "Furthermore, our group also demonstrated that ORAI1 silencing is responsible for cell-cycle blockade due to decreased expression of cyclin D1 in prostate cancer cell lines." (PMID 34831241, 2021). "Moreover, the expression levels of STIM1 and Orai1 and other homologs are found to be differentially regulated based on the prostate cancer stage." (PMID 33333945, 2020). "In contrast, in prostate cancer, which could be the only exception, Orai1 expression was decreased when compared to normal tissue but was increased when compared to hyperplasia." (PMID 31252656, 2019). "In addition, Orai1 downregulation has been shown to contribute to the formation of an apoptosis-resistant phenotype in prostate cancer cells." (PMID 30935064, 2019). "Moreover, the expression of exogenous Orai1 in the androgen-independent prostate cancer cells, which express a low level of Orai1 accompanied with attenuated SOCE, was found to restore the normal rate of apoptosis of these cells." (PMID 31252656, 2019). "In addition, the lipid mediator arachidonic acid (AA) promotes the store-independent interaction of Orai1 with Orai3 in prostate cancer cell lines, which leads to SOCE down-regulation and promotes cell proliferation." (PMID 30123430, 2018). "They proposed that remodeling of Orai1/Orai3 may constitute as an oncogenic switch in prostate cancer." (PMID 25481035, 2015).
prostate carcinoma (continued). "At the same time, the expression of ORAI1 reduced in prostate cancer when compared with normal and hyperplasia tissues and when the cancer progressed from low to high Gleason scores, indicating the prohibitive effect of ORAI1 on development of prostate cancer." (PMID 26257076, 2015). "All these data suggest that the overexpression of STIM1 and/or ORAI1 may promote cell senescence in prostate cancer cells." (PMID 26257076, 2015). "Orai3 is significantly down-regulated and the decrease in Orai1:Orai3 ratio might reflect a different stoichiometry of Orai1/Orai3 subunits in CRAC channel that open the possibility for specific therapeutic targeting in prostate cancer." (PMID 24240085, 2013). "Furthermore, low Orai1 expression may contribute to an apoptosis-resistant phenotype in prostate cancer cells." (PMID 29951353, 2017). "We found that the vast majority of prostate cancer CTCs had simultaneously both STIM1 and ORAI1 overexpression (94%)." (PMID 38903530, 2024). "Based on the previous data the current study investigated at protein level the expression of ORAI1, STIM1, and KDM2B in CTCs from prostate cancer patients." (PMID 38903530, 2024). "We demonstrate that the synergy of Orai1 and SK3 occurs not only in HEK 293 cells, but also exists in prostate cancer cells, where it likely regulates the function and growth." (PMID 34944977, 2021). "This change in the Orai3/ Orai1 expression dynamic created a shift from the use of the canonical Orai1-based SOCE and marks the oncogenic switch that facilitates prostate cancer tumor progression." (PMID 32599788, 2020). "In androgen-independent, apoptosis-resistant prostate cancer cells, such remodeling was shown to involve reduced SOCE via downregulation of Orai1 or Stim1 proteins, and adaptation of the ER to the conditions of reduced Ca2+ storage and uptake." (PMID 30884858, 2019). "The essential role of the functional coupling of STIM1 to Orai1, as well as STIM1/Orai1-dependent SOCE, in promoting apoptosis was firstly demonstrated in the study on prostate cancer cells." (PMID 31252656, 2019). "Similar SOCE elevations were also seen in STIM1 + Orai1-OE and only STIM1-OE DU145 (prostate cancer cell line) and HEK (human embryonic kidney) cells, respectively." (PMID 31366337, 2019). "This article summarizes what is known about the dysregulation of the key molecular players involved in SOCE (STIM1, STIM2, Orai1, Orai2, and Orai3) and the negative regulator TRPM4 in prostate cancer." (PMID 29951353, 2017). "To further investigate the role of STIM1 and ORAI1 in prostate cancer, we established DU145 and PC3 cell lines that stably overexpressed STIM1-YFP and/or ORAI1." (PMID 26257076, 2015). "Other work in human prostate cancer cells has shown that normal expression of Orai1 and SOCE are critical in maintaining the rate of apoptosis and thus, resistance to prostate cancer." (PMID 24000152, 2013). "However, in one study, it was shown that cisplatin cytotoxicity was reduced upon knockdown of ORAI1 and STIM1 in NSCLC and prostate cancer cells." (PMID 38510751, 2024). "Similarly, in prostate cancer cells Orai1 knockdown inhibited apoptosis and STIM1 or Orai1 expression enhances cell senescence, thus supporting a role for SOCE in cancer cell death." (PMID 34069353, 2021). "Genetic silencing of STIM1/Orai1 and STIM1/Orai3 protein complexes by siRNA interference has, for example, yielded promising reductions in tumour progression and metastasis in xenograft models of breast, cervical and prostate cancer." (PMID 33036292, 2020). "In addition to the reviewed roles of calcium-release activated calcium channel protein ORAI1 in senescence and SOCE, the channel appears to be involved also in the capacitative entry mediating apoptosis in androgen-sensitive prostate cancer cells in culture." (PMID 29671777, 2018).
prostate carcinoma (continued). "First, application of 2-APB, which blocks currents via Orai1 and enhances currents via Orai3, resulted in stronger amplification of ICRAC in primary human prostate epithelial cells (hPECs) from healthy tissue compared to prostate cancer cells." (PMID 29951353, 2017). "We find a significant down-regulation of Orai3 gene expression in tumorous tissue when compared to non-tumerous tissue from prostate cancer patients and an increased Orai1:Orai3 ratio." (PMID 24240085, 2013). "We compare expression levels of STIM1, STIM2, Orai1, Orai2 and Orai3 in tumorous and non-tumorous tissue from prostate cancer patients." (PMID 24240085, 2013). "Resveratrol has been reported to promote autophagy in prostate cancer cells by down-regulating STIM1 and down-regulating SOCE, but the expression of ORAI1 and TRPC1 was not affected during this process." (PMID 31426853, 2019). "We thus determined relative STIM and Orai expression levels in non-tumorous and tumorous tissue from 13 prostate cancer patients by qRT-PCR, from which 13 expressed detectable levels of STIM1, STIM2 and Orai1 and 11 detectable levels of Orai2 and Orai3." (PMID 24240085, 2013). "In addition, a comparison of Orai1:Orai3 gene expression ratios and electrophysiological profiles upon application of 2-APB in prostate cancer cell lines LNCaP, DU145 and hPEC support the idea of low levels of Orai3 in prostate cancer, although Orai3 is not reduced per se in cancer." (PMID 24240085, 2013).
colon cancer (24 papers, 2016 to 2024). "It was also demonstrated that the SK3 potassium channel, in association with TRPC1 and Orai1 calcium channels, regulated colon cancer cell migration." (PMID 30884858, 2019). "Additionally, hypoxia-induced cell migration and invasion in triple-negative breast cancer cells and colon cancer cells have been linked to the Notch1/ORAI1/SOCE/NFAT4 pathway." (PMID 38672434, 2024). "Accumulation of SK3/Orai1 or TRPC1/SK3/Orai1 complexes in lipid rafts promotes Ca2+ entry and the migration or breast or colon cancer cells, while disruption of lipid rafts impairs Ca2+ entry and cell migration." (PMID 39429488, 2024). "In fact, knockdown of SigmaR1 or use of the ligand igmesine, which inhibits SigmaR1, abolished the SK3/Orai1 interplay of channels in cholesterol-rich nanodomains in breast and colon cancer cells." (PMID 35327543, 2022). "In contrast, colon cancer cell migration is manifested through the formation of a triple channel complex of the TRPC1/Orai1/SK3 channels in cholesterol-rich regions, which is further facilitated by STIM1." (PMID 36612099, 2022). "Despite the interplay between SK3 and Orai1 being extensively studied in breast and colon cancer cells (see Section 4.1.2), the molecular determinants required for their co-regulation are poorly characterized." (PMID 36612099, 2022). "In colon cancer progression, hypoxia augmented Orai1 and Orai3 expression as well as SOCE by increasing the expression of the hypoxia-dependent transcription factor HIF-1/2." (PMID 36612099, 2022). "Co-localization of SK3 with Orai1 has been detected via co-immunoprecipitation in breast and colon cancer cells." (PMID 36612099, 2022). "While normal human breast and colon cancer cells contain only Orai1, the corresponding cancer cells express SK3 and Orai1 co-localized in lipid rafts." (PMID 34944977, 2021). "Recent studies have reported the co-localization of the SK3 and Orai1 channels in breast and colon cancer cells." (PMID 34944977, 2021). "While SigmaR1 and STIM1 interact directly in HEK 293 cells, in breast and colon cancer cells, this receptor associates directly with SK3 and triggers a close association of Orai1 and SK3." (PMID 33333945, 2020). "In support, downregulation of SigmaR1 or the application of an inhibitory SigmaR1 ligand igmesine in breast and colon cancer cells has abolished the interplay of SK3 with Orai1 channels in lipid rafts and decreased their levels in lipid nanodomains." (PMID 33333945, 2020). "In the review, another difference between normal and colon cancer cells is that SOCE in normal colonic cells involves only ORAI1-mediated CRAC channels." (PMID 32733237, 2020). "In the present study, we demonstrate that SOCE promotes migration of colon cancer cell following the formation of a lipid raft ion channel complex composed of TRPC1/Orai1 and SK3 channels." (PMID 27102434, 2016). "Taken together, these data suggest that SOCE induced by STIM1/Orai1/TRPC1 plays a role in SK3-dependent colon cancer cell migration." (PMID 27102434, 2016). "In colon cancer and triple-negative breast cancer, hypoxia upregulated ORAI1 by the Notch1 pathway." (PMID 38672434, 2024). "These include the plasma membrane Ca2+ ATPase (ATP2B4), the purinergic receptor subtype P2RY2A and the calcium channel ORAI1, all upregulated in colon cancer and the calcium voltage-gated channels CACNA1H and CACNA1Cn were found to be downregulated in colon cancer." (PMID 35267511, 2022). "Recent studies have further indicated that hypoxia can induce the activation of NFATc3 in colon cancer cells via upregulation of Orai1, which leads to increased intracellular Ca2+ and NFATc3 nuclear anchorage, resulting in the transcriptional activation of downstream genes." (PMID 35484132, 2022). "Furthermore, Cav-1 was reported to further contribute to STIM1/TRPC1/Orai1/SK3 complex formation in colon cancer." (PMID 35327543, 2022).